STAT1 (signal transducer and activator of transcription 1)
Diseases named in the same sentence as STAT1 in open-access papers (continued):
Sharing a sentence is not in itself a finding about the gene and the disease.
fungal infections (continued). "The hyperactivity of STAT1 in response to IFNs and IL-27 signals associates with PD-L1 up-regulation, reduced expression of STAT3-dependent genes including SOCS3, and, consequently, inhibition of Th17 differentiation that leads to the susceptibility to fungal infections." (PMID 38578354, 2024). "STAT1 GOF mutations are associated with an increased incidence of certain tumor entities, some of which may be explained by persistent mucocutaneous fungal infections that develop into squamous cell carcinoma (cutaneous, oral, laryngeal, esophageal, gastrointestinal cancer)." (PMID 37140667, 2023). "Patients with STAT1 GOF most commonly exhibit early-onset CMC and other bacterial, viral, and fungal infections, and may also experience autoimmune or autoinflammatory conditions." (PMID 38578320, 2024). "Endemic fungal infections have been reported in AR IL12Rβ1, AR IFN-γR1, and AD GOF STAT1 defects." (PMID 28702025, 2017). "However, this patient did not carry any variants in CARD9, IL17RA, L17RC, IL17F, STAT1, DOCK8, MALT1, or TRAF3IP2 genes that can explain the susceptibility to a severe and invasive fungal infection." (PMID 35091979, 2022). "However, some authors have reported the therapeutic failure of ruxolitinib in treating severe fungal infections other than CMC, or early-onset inflammatory bowel disease, suggesting that larger cohort studies are recommended to support the efficacy of JAK inhibitors in STAT1-GOF patients." (PMID 38578354, 2024).
fibrosarcoma (23 papers, 2011 to 2024). A malignant mesenchymal fibroblastic neoplasm affecting the soft tissue and bone. "This notion derives from the variant-specific IFN-α and IFN-γ gene expression patterns that were caused by two different STAT1 GOF variants in a STAT1-deficient U3A fibrosarcoma cell line transfection model." (PMID 39114664, 2024). "The tumor-suppressive role of STAT1 has been previously demonstrated, whereby reconstitution of STAT1 in STAT1-deficient murine fibrosarcoma cells significantly suppressed tumorigenicity and metastasis in nude mice." (PMID 34282238, 2021). "We evaluated the participation of STAT1 to the cellular response following DNA damage induced by MNNG in human STAT1‐proficient (STAT1+/+) or ‐deficient (STAT1−/−) fibrosarcoma cell lines." (PMID 27464833, 2016). "STAT1 induces cell cycle arrest in response to interferon-γ by interacting with D-type cyclins and cyclin-dependent kinase-4 in fibrosarcoma cells." (PMID 35781872, 2022). "Activated Stat1 have been reported to directly interact with cyclin D1 to promote its proteasomal degradation in fibrosarcoma cancer cells." (PMID 33046973, 2020). "It is known that loss of TH1 associated signals, such as IFN-γ, IFN receptors, STAT-1, and IL-12p40, lead to increased susceptibility to MCA induced fibrosarcomas." (PMID 23554861, 2013). "In a human fibrosarcoma cell line, IRF 1 (irf1) has been found to be induced substantially only by type II IFN,and a strong modulation of this transcript is now considered as a hallmark of Stat1 dimer signaling/GAS-specific ISG." (PMID 31142600, 2019). "In contrast, the induction of these ISGs is abrogated in STAT1 knockout fibrosarcoma cells." (PMID 27929099, 2016). "To test whether STAT2 interferes with STAT1 DNA binding, we used electrophoretic mobility shift assays (EMSAs) with extracts from STAT2-deficient human U6A fibrosarcoma cells and stable derivatives expressing WT STAT2 or mutant STAT2-L82A." (PMID 27780205, 2016). "Dependency on STAT1 was confirmed by the lack of expression in IL-27-treated U3A cells, a STAT1-deficient human fibrosarcoma line." (PMID 27780205, 2016). "Although we have found that more p300/CBP co-activator is recruited to the ISG transcriptional complex in STAT1-CC transduced fibrosarcoma cells, the acetylation level of STAT1-CC remains unclear." (PMID 26351076, 2015). "To test the possibility that βV665A activates STAT1 via JAK2, we first used γ2A fibrosarcoma cells, which lack JAK2 and are therefore unresponsive to interferon γ." (PMID 35689379, 2022). "Compared to wild-type (2fTGH, fibrosarcoma) cells, DRAK1 induction was significantly reduced in STAT1-defective cells (U3A, derived from 2fTGH and defective in type I IFN signaling), while DRAK2 levels remained unchanged." (PMID 31330998, 2019). "For example, STAT1 specifically interacts with cyclin D1 and CDK4 to mediate cell cycle arrest in a human fibrosarcoma cell line after treatment with interferon (IFN)-γ." (PMID 28716119, 2017). "Using RNAi to knockdown STAT1 in HCT116 cells and U3A, a STAT1-null sub-line of fibrosarcoma cell line 2fTGH, we previously showed that STAT1 was not required for, but augmented, the expression of IRF9 and IRDS genes induced by high cellular density." (PMID 30679726, 2019).
osteosarcoma (23 papers, 2003 to 2025). A usually aggressive malignant bone-forming mesenchymal neoplasm, predominantly affecting adolescents and young adults. "Having confirmed the detrimental effect of HTR2B and STAT1 on osteosarcoma, we focused on discovering the underlying molecular mechanisms." (PMID 40387572, 2025). "H3K27 acetylation activated‐COL6A1 promotes osteosarcoma lung metastasis by repressing STAT1 and activating pulmonary cancer‐associated fibroblasts." (PMID 37143582, 2023). "Increased expression of COL6A1 promoted STAT1 degradation, which subsequently facilitated osteosarcoma metastasis." (PMID 37197432, 2023). "The activation of STAT1 in osteosarcoma cells suppressed EMT, resulting in increased apoptosis and cell cycle arrest, and decreased colony formation, cell migration, and invasion." (PMID 37197432, 2023). "Consistently, we found that TGF-β attenuated STAT1 phosphorylation to suppress SDH in osteosarcoma cells." (PMID 34763667, 2021). "Mechanistically, we demonstrated that TGF-β caused a decrease in STAT1 to inhibit the metabolic enzyme succinate dehydrogenase (SDH), giving rise to succinate accumulation in osteosarcoma cells." (PMID 34763667, 2021). "More importantly, STAT1 is a transcription factor in the interferon signaling pathway—a pathway known to be involved in osteosarcoma, and for which targeted treatment options are available." (PMID 31653243, 2019). "Protein–protein interaction analysis suggested that STAT1 may be a potential downstream‐acting molecule of HTR2B activation suppresses osteosarcoma progression." (PMID 40387572, 2025). "To further investigate the role of STAT1 in osteosarcoma, we used the lentivirus to downregulate the expression of STAT1, the RT‐qPCR and western blot results confirmed that the mRNA and protein expression STAT1 is effectively downregulated after lentivirus transfection in osteosarcoma cells." (PMID 40387572, 2025). "Moreover, Combined the overexpression of HTR2B and knockdown of STAT1 can further suppresses osteosarcoma progression via NLRP3 inflammasome." (PMID 40387572, 2025). "Consistent with our findings that increased proliferation, invasion, and migration of the HCC cell line SMMC-7721 were significantly inhibited after transfection of STAT1-siRNA into HCC cells, inhibition of STAT1 expression was reported to promote metastasis of osteosarcoma." (PMID 35692770, 2022). "Consistently, STAT1 levels were reduced in chemoresistant tumor tissues from osteosarcoma patients." (PMID 34763667, 2021). "CLDN10 is highly expressed in osteosarcoma cells compared with fetal osteoblast cells, and CLDN10 overexpression in osteosarcoma cells enhances the JAK1/STAT1 signaling pathway to significantly promote proliferation and motility." (PMID 36620607, 2022). "Recent studies have highlighted TYK2 can act as an oncogene, with TYK2 activation increasing STAT1 phosphorylation and the expression of BCL-2 in T-cell acute lymphoblastic Leukemia and osteosarcoma." (PMID 35152270, 2022). "We detected the expression of succinate dehydrogenase (SDH), STAT1, and hypoxia-inducible factor 1α (HIF1α) in TGF-β-treated osteosarcoma cells and further tested the effects of these molecules on the cytotoxicity induced by chemotherapeutic agents." (PMID 34763667, 2021). "Human osteosarcoma U2OS cells were infected with a low multiplicity of infection (MOI) to leave some cells uninfected, allowing us to evaluate STAT1 phosphorylation in both infected and naïve cells from the same cultures." (PMID 26196739, 2015). "We treated the human osteosarcoma cell line U2OS with different radiation doses (2-20 Gy), and measured IFN signaling three to six days post treatment by immunoblotting of phosphorylated STAT1 (pSTAT1)." (PMID 36387237, 2022). "In addition, reduced nuclear entry of STAT1 in TGF-β-treated Saos-2 and MG-63 cells was found by immunofluorescence staining, suggesting that TGF-β suppressed STAT1 activation in osteosarcoma cells." (PMID 34763667, 2021).
osteosarcoma (continued). "Thus, miR-483 inhibited the EMT of osteosarcoma cells by restraining STAT3 expression and inducing STAT1 expression." (PMID 33546665, 2021). "However, NEAT1 sponged miR-438, increased STAT3 expression, and repressed STAT1 expression, subsequently increasing the EMT of osteosarcoma cells." (PMID 33546665, 2021). "Thus, a low STAT3/STAT1 ratio indicated the impaired migration, invasion and EMT of osteosarcoma cells, consistent with a previous report describing the correlation between STAT3/STAT1 ratio and patient survival." (PMID 33546665, 2021). "STAT1 is a key transcription factor in this pathway, and our observation that STAT1 and p-STAT1 levels were maintained in HOS and U2OS cells supports that osteosarcoma cells are intrinsically resistant to SINV infection, which may contribute to their low permissiveness." (PMID 41438132, 2025). "Notably, both WiDr and PM1 cells responded with induction of STAT1 after incubation with 50 U ml−1 IFN-γ for 48 h (results not shown), suggesting that the difference in S100A4 response could not be explained by increased sensitivity to IFN-γ in the osteosarcoma cells in general." (PMID 12799648, 2003).
type 1 diabetes (23 papers, 2013 to 2025). "A case report showed that JAK1/JAK2 inhibitor ruxolitinib normalized blood-glucose levels and discontinued exogenous insulin in a patient with type 1 diabetes caused by STAT1 gain-of-function." (PMID 35242127, 2022). "STAT1 has been previously associated with type 1 diabetes, which is caused by pancreatic β-cells destruction via cytokine-mediated apoptosis." (PMID 33004927, 2020). "The response is closely associated with elevated expression of STAT1 and, together, these occur uniquely in patients with type 1 diabetes, thereby contributing to their selective susceptibility to autoimmune-mediated destruction." (PMID 27506584, 2016). "STAT1 mutation was closely related to type 1 diabetes susceptibility." (PMID 31881887, 2019). "In type 1 diabetes upregulation of HLA class I is strongly associated with an increased expression of the interferon-responsive transcription factor, signal transducer and activator of transcription 1 (STAT1), a critical protein involved in mediating interferon response to viruses." (PMID 35957810, 2022). "In pancreatic tissue from recent-onset type 1 diabetes patients, a positive correlation between islet cell staining of HLA-A/B/C and STAT1 was observed." (PMID 37113489, 2023). "A recent review summarized the roles of STAT (STAT1, STAT3 and STAT5b) monogenic mutations in type 1 diabetes." (PMID 35242127, 2022). "Recent findings demonstrate that STAT1 expression is positively correlated with HLA-ABC hyperexpression in type 1 diabetes." (PMID 28881828, 2017). "Most remarkably, we identify a common missense variant in IL27, associated with type 1 diabetes that results in decreased functional activity of the protein and reduced expression levels of downstream IRF1 and STAT1 in CD4+ T cells only." (PMID 28248954, 2017). "An important additional new finding in the present work is the striking correlation between the levels of STAT1 measured in the beta cells of patients with type 1 diabetes and HLA-I hyperexpression." (PMID 27506584, 2016). "STAT1 is a critical protein involved in mediating antiviral responses to IFNs, and its early upregulation in the progression of type 1 diabetes would be expected to place beta cells in a heightened state of responsiveness to these cytokines." (PMID 27506584, 2016). "Furthermore, their research indicated that MBD2 functions as a repressor to maintain the homeostasis of the Th1 program in type 1 diabetes by regulating the STAT1–IFN-γ axis." (PMID 41258082, 2025). "Importantly, STAT1 expression is elevated in the beta-cells of donors with recent-onset type I diabetes, and this correlates with HLA-I hyperexpression on an islet-by-islet basis." (PMID 37867531, 2023). "STAT1 expression was also low in the IDIs of type 1 diabetes donors." (PMID 27506584, 2016). "The risk of type 1 diabetes (T1D) is higher in patients with IPEX (FOXP3, forkhead box P3), WHIM syndrome, autoimmune polyglandular syndrome type 1 (APS type 1 due to AIRE mutation), CTLA4 mutation, deficiency of LRBA, milder forms of ADA deficiency, and STAT1 GOF." (PMID 37102642, 2023). "It is, therefore, a reasonable working hypothesis that both the hyperexpression of HLA class I and the upregulation of STAT1 observed in the β-cells of type 1 diabetes donors occur as a consequence of viral infection, and that both features serve as “viral footprints” in the endocrine pancreas." (PMID 35957810, 2022). "Another study reported increased expression of several genes typically induced by type I and II IFNs including STAT1, CXCL10 and HLA-I in islet tissue of living individuals with recently diagnosed type 1 diabetes." (PMID 37113489, 2023). "Preliminary studies revealed a strong correlation between STAT1 and HLA-ABC expression in type 1 diabetes." (PMID 28881828, 2017).
type 1 diabetes (continued). "Our data provide additional details regarding the IFN-α-signaling pathway during type I diabetes based on the use of antibodies to label proteins downstream of IFNAR1, such as STAT1, STAT2, AKT, and IκB-α." (PMID 23533683, 2013). "Importantly, however, cytosolic STAT1 expression was not increased in the non-beta islet endocrine cells in type 1 diabetes, despite these having elevated HLA-I." (PMID 27506584, 2016).
inflammatory bowel disease (22 papers, 2014 to 2026). A spectrum of small and large bowel inflammatory diseases of unknown etiology. "For example, Astragaloside IV (AS-IV) binds to STAT1 and promotes its dephosphorylation at Tyr701, facilitating M2 macrophage polarization in inflammatory bowel disease." (PMID 41375527, 2025). "In inflammatory bowel disease, ErbB4 is involved in the regulation of inflammatory M1/M2 transformation through the interaction with STAT1 and STAT5." (PMID 37800117, 2023). "Inflammatory bowel disease and endocrine anomalies were frequently observed in our patients with CVID, STAT1 mutations, and auto-inflammation." (PMID 32670274, 2020). "Topological analysis identified 14 core targets based on centrality metrics, and five key intersection genes (CASP7, BIRC5, CDK9, STAT1, RELA) were highlighted as significantly associated with core network functions, including inflammatory bowel disease and apoptosis." (PMID 41515060, 2025). "This study aimed to investigate whether activation of PPARγ regulates M1/M2 macrophage polarization to attenuate dextran sulfate sodium salt (DSS)‐induced inflammatory bowel disease (IBD) via the STAT‐1/STAT‐6 pathway in vivo and in vitro." (PMID 39737788, 2025). "Octanoic acid‐rich enteral nutrition could regulate the M1/M2 polarization of intestinal macrophages and simultaneously repair the intestinal mucosal barrier by activating the PPARγ/STAT‐1/STAT‐6 pathway, thereby significantly alleviating inflammatory bowel disease‐induced intestinal injury." (PMID 41256230, 2025).
primary immunodeficiency (22 papers, 2013 to 2025). "Inborn errors of immunity (IEIs) caused by mutations in STAT1 are associated with a broad range of clinical manifestations, ranging from relatively mild to life-threatening." (PMID 40881691, 2025). "In the course of treatment, the child was found to have primary immunodeficiency disease through genetic testing, accompanied by STAT1 LOF gene mutation." (PMID 40980136, 2025). "On November 12, 2019, the patient underwent a complete Maikino exon examination during outpatient follow-up in our hospital, and the examination results indicated that the patient had primary immunodeficiency disease accompanied by STAT1 LOF gene mutation." (PMID 40980136, 2025). "At outpatient follow-up, the patient was found to have primary immunodeficiency disease with STAT1 LOF mutation." (PMID 40980136, 2025). "This boy was diagnosed with primary immunodeficiency caused by STAT1 R274W mutation, with proofs of WES and sanger sequencing." (PMID 36891307, 2023). "The AR characterized by biallelic complete LOF mutations of STAT1 and complete STAT1 deficiency is a rare autosomal recessive primary immunodeficiency." (PMID 35456913, 2022). "Therefore, we need to be alert to BCG osteomyelitis when we encounter unexplained fever and bone destruction in infants with primary immunodeficiency disease associated with STAT1 LOF mutation." (PMID 40980136, 2025). "Similar modifier gene effects have been described in other primary immunodeficiencies, such as DOCK8 deficiency and STAT1 GOF mutations, where additional genetic variants contribute to phenotypic variability and disease severity." (PMID 40951253, 2025). "As expected, both patients had complained of mucosal candidiasis, which should have raised the suspicion of a primary immunodeficiency like STAT1 GOF." (PMID 33971891, 2021). "Sanger sequencing from all affected individuals in the family revealed a novel heterozygous signal transducer and activator of transcription 1 (STAT1) mutation in exon 22 at c.1957G>A, while genetic testing for mutations in 276 other known genes involved in primary immunodeficiency was negative." (PMID 28348565, 2017).